HBB (hemoglobin subunit beta)
Diseases named in the same sentence as HBB in open-access papers (continued):
Sharing a sentence is not in itself a finding about the gene and the disease.
cystic fibrosis (6 papers, 2013 to 2025). Autosomal recessive disorder caused by pathogenic variants in the CFTR gene (cystic fibrosis transmembrane conductance regulator), which encodes a chloride and bicarbonate channel expressed in epithelial cells, and follow the diagnosis criteria. "Furthermore, the panel used for the screen does not cover the entirety of each of the target genes responsible for cystic fibrosis (CFTR) or haemoglobinopathies (HBB)." (PMID 39698301, 2023). "This technology was first reported in the context of NIPD for several autosomal recessive conditions, including cystic fibrosis (CFTR), β-thalassaemia (HBB), and congenital adrenal hyperplasia (CYP21A2)." (PMID 39698301, 2023). "In particular, for molecular genetic testing, it offers specific EQA schemes for 4 diseases: Cystic Fibrosis (CFTR gene), Beta Thalassemia (HBB gene) (BT), Fragile X-Syndrome (FMR1 gene) (FX), and Familial Adenomatous Polyposis Coli (APC gene) (APC)." (PMID 23484150, 2013).
erythrocytosis (5 papers, 2020 to 2023). "We present a long-term survey of pediatric liver recipients, evaluating prevalence, outcome and the main potential causes of erythrocytosis, including a comprehensive mutational analysis of commonly related genes (mutations of HBB and HBA, JAK2, EPOR, VHL, EPAS1 and EGLN1)." (PMID 32546701, 2020). "Up to now, two types of erythrocytosis have been associated with mutations in hemoglobin genes, HBA1, HBA2 (ECYT7) and HBB (ECYT6) respectively, however hemoglobin variants do have diverse pathophysiology." (PMID 34440324, 2021). "To discover genetic variants in unexplained erythrocytosis, we performed whole exome sequencing in 27 patients with JAK2-negative polycythemia after excluding the presence of any mutations in genes previously associated with erythrocytosis (EPOR, VHL, PHD2, EPAS1, HBA, and HBB)." (PMID 37428608, 2023). "Therefore, we recommend the systematic sequencing of the HBB, HBA1 and HBA2 genes in the exploration of idiopathic erythrocytosis." (PMID 35052472, 2022). "We sequenced the HBB, HBA1 and HBA2 genes of 75 patients with idiopathic erythrocytosis." (PMID 35052472, 2022). "The HBB, HBA1 and HBA2 genes were not part of our initial NGS panel since in our initial diagnostic strategy, blood gases were performed as part of the screening workup for erythrocytosis." (PMID 35052472, 2022).
adenoma (4 papers, 2005 to 2023). A neoplasm arising from the epithelium. "We found lower levels of beta hemoglobin (HBB) RNA in adenomas compared to normal mucosa in this study as well as in another gene profiling study we have performed (manuscript in preparation)." (PMID 15982419, 2005). "Among the proteins detected in adenomas at baseline and after the Aspirin treatment, the changes in vimentin and HBB (hemoglobin subunit beta) were the most relevant responses to the drug treatment." (PMID 37173923, 2023). "Meanwhile, hemoglobin (HBA1, HBB or HBD) was not significantly differential between high‐risk adenomas and controls, and subsequently it was not selected in any of the biomarker panels, which is in line with the limited sensitivity of FIT for adenomas." (PMID 31784980, 2020).
beta-thalassemia intermedia (4 papers, 2017 to 2024). Beta-thalassemia (BT) intermedia is a form of BT characterized by mild to moderate anemia which does not or only occasionally requires transfusion. "The second family presented also thalassemia intermedia phenotype, however, theirmolecular basis included two β globin gene mutations: the typicalHBB.c:118C > T and a new uncharacterized deletion involvingthe 3’ end of HBB gene." (PMID 32142096, 2020).
iron overload (4 papers, 2018 to 2022). "Medical records indicated hemochromatosis in 1.6% of HBB LoF heterozygotes vs. 0.4% of those without HBB LoF variants, 2.4% vs. 0.007% had hepatic fibrosis, and 2.2% vs. 0.3% had nonalcoholic cirrhosis, indicating that complications of iron overload can be a concern for HBB LoF heterozygotes." (PMID 34385667, 2021).
melanoma (4 papers, 2014 to 2025). A malignant, usually aggressive tumor composed of atypical, neoplastic melanocytes. "These include hemoglobin genes (HBB, HBG1, HBG2) in the peripheral blood-derived cell line KU812, MIA (melanoma inhibitory activity) in the melanoma-derived cell line A375 as well as insulin (Ins1, Ins2) and islet amyloid polypeptide (Iapp) in the mouse pancreatic beta cell line Beta-TC6." (PMID 28687070, 2017).
ovarian carcinoma (4 papers, 2020 to 2025). A malignant neoplasm originating from the surface ovarian epithelium. "A recent study has shown that hemoglobin subunit alpha 1 (HBA1) and hemoglobin subunit beta (HBB) levels were significantly elevated in patients with ovarian cancer compared to healthy patients." (PMID 38067210, 2023). "According to reports, HBB expression in the serum of ovarian cancer patients is higher than in normal controls, suggesting that it could be used as a potential diagnostic marker for the disease." (PMID 40496615, 2025). "Hemoglobin subunit beta (HBB) is a member of the globin family and a structurally conserved group of proteins often containing the heme group, which has been identified as a potential serum biomarker for the diagnosis and prognosis of ovarian cancer." (PMID 35847888, 2022).
prostate carcinoma (4 papers, 2017 to 2024). A carcinoma that arises from epithelial cells of the prostate gland. "Previous reports have shown that TBX15 expression can be used as a prognostic marker for HCC, and HBB has been reported to play a key role in prostate cancer differentiation and in a variety of important biological pathways (e.g., iron metabolism)." (PMID 34458266, 2021). "In the immune cell cluster of prostate cancer, formononetin targeted CD74, TNF, HBB, THBS1, INSR, CXCR4, and HSP90AA1." (PMID 38874510, 2024).
Stroke (4 papers, 2012 to 2025). Sudden impairment of blood flow to a part of the brain due to occlusion or rupture of an artery to the brain. "In particular, the three DElncRNAs (CTD-2545M3.2, RP11-24N18.1, and RP11-473C18.7) and four DEGs (LCN2, LAIR2, RPS10, and HBB) that showed the most significant variations between PSA and HC samples were selected for further qPCR verification in the samples from the HC, stroke, PSA, and PSA-T groups." (PMID 40270596, 2025).
G6PD deficiency (3 papers, 2005 to 2024). An X-linked genetic condition caused by alterations in the gene G6PD that result in moderately to severely decreased activity levels of the enzyme glucose-6-phosphate dehydrogenase. "In addition, samples were genotyped for glucose-6-phosphate dehydrogenase deficiency (G6PDd) and sickle cell trait (HbB-rs334-T/A); both of which are associated with resistance to blood stage malaria infection." (PMID 33882912, 2021). "Mutations in the haemoglobin beta-globin (HbB) and glucose-6-phosphate dehydrogenase (G6PD) genes cause widespread human genetic disorders such as sickle cell diseases and G6PD deficiency." (PMID 16356170, 2005).
hepatocellular carcinoma (3 papers, 2023 to 2025). A malignant tumor that arises from hepatocytes. "Furthermore, the overexpression of hemoglobin (HBA1 and HBB) in the rat renal mesangial and human hepatocellular cancer cell lines alleviates H2O2-induced oxidative stress, leading to enhanced cell viability under oxidative stress conditions." (PMID 38067210, 2023).
Iron deficiency anemia (3 papers, 2020 to 2021). "Additionally, since the high expression of HBB and HBA were found at the end stage of erythrocytes and MCV did not display a declining trend, iron deficiency could not have been the main cause of impairment in erythrocyte maturation." (PMID 34113638, 2021).
neuroblastoma (3 papers, 2023 to 2025). Neuroblastoma (NB) is the most common solid, extracranial childhood tumor. "Additionally, the expression of HBB is significantly higher in colorectal cancer, and HBB2/HBB is implicated in the regulation of tumorigenesis and metastasis in neuroblastoma." (PMID 38067210, 2023). "A similar result was observed that induced HBB expression inhibited growth and metastasis of neuroblastoma, suggesting the anti-tumor roles of HBB." (PMID 38874510, 2024).
periodontitis (3 papers, 2022 to 2024). An acute or chronic inflammatory process that affects the tissues that surround and support the teeth. "In this study, SNCA, CA1, SLC4A1, ANK1, and HBB were identified as hub proteins associated with periodontitis progression." (PMID 38802345, 2024). "In addition, specific biological processes and molecular functions during progressive periodontitis were revealed and a set of hub proteins, including SNCA, CA1, HBB, SLC4A1, and ANK1 was strongly associated with the clinical progression status of periodontitis." (PMID 38802345, 2024). "Herein, SNCA, CA1, HBB, SLC4A1, and ANK1, were identified as hub proteins of periodontitis progression." (PMID 38802345, 2024). "Spatial transcriptomics revealed significant upregulation of ACTB, GSTO1, RAB1B, HBB, DMKN, and CTSZ in basal epithelial cells during periodontitis." (PMID 39769019, 2024).
anaplastic thyroid cancer (2 papers, 2020 to 2024). "A study on gene expression profile of anaplastic thyroid cancer cell lines (ACL) showed significant reduced expression of HBB in ACL." (PMID 38874510, 2024). "In anaplastic thyroid cancer cell lines (ACL), HBB expression is also found significantly decreased." (PMID 32695162, 2020).
bladder cancer (2 papers, 2023). "In the second biomarker discovery study to detect a biomarker panel to monitor bladder cancer patients in follow-up, only HBB and HBA1 were identified as statistically significant biomarkers with an absolute fold change larger than 0.6 and an FDR-corrected p value smaller than 0.05." (PMID 37371512, 2023). "Notably, the expression of HBA1 and HBB is significantly higher in cervical and bladder cancer tissues than in normal cervix tissues." (PMID 38067210, 2023). "Additionally, two proteins (HBB and HBA1) were differentially expressed between bladder cancer patients with a recurrent diagnosis vs. tumor-free samples of bladder cancer patients, but their biological relevance is very limited." (PMID 37371512, 2023). "HBA1 and HBB were the only statistically significant biomarkers with an absolute fold change larger than 0.6 and an FDR-corrected p value smaller than 0.05 in the other biomarker discovery study with bladder cancer patients with a recurrence diagnosis and tumor-free patients in follow up." (PMID 37371512, 2023).
blood disease (2 papers, 2015 to 2022). A disease that occurs in the blood. "β-Thalassemia is one of the most common genetic blood diseases and is caused by either point mutations or deletions in the β-globin (HBB) gene." (PMID 26156589, 2015). "The researchers modified hemoglobin beta (HBB), the gene that causes the blood disease β-thalassemia when it becomes non-functional, using tripronuclear human zygotes." (PMID 36429042, 2022).
brain tumor (2 papers, 2015 to 2020). "Comparing our proteomic analysis with previous proteomic works on medulloblastoma and brain tumor exosomes, many proteins are shared, as expected: ACTB, G3P, GRP78, ANXA2, TRFE, CH60, HBB, HSP90." (PMID 26464805, 2015).
glaucoma (2 papers, 2021 to 2024). Increased pressure in the eyeball due to obstruction of the outflow of aqueous humor. "HBB protein levels seem to be positively correlated with visual field index parameters in glaucoma patients." (PMID 39000104, 2024). "In agreement with our results, the downregulation of FGA (fibrinogen alpha chain), FGG (fibrinogen gamma chain), and HBB (hemoglobin subunit beta) was assessed in primary open-angle glaucoma patients’ aqueous humor." (PMID 39000104, 2024).
haemolytic anaemia (2 papers, 2016 to 2023). "For example, we found that two predicted LOF variants in HBB p.Glu7Lys and p.Glu27Lys were associated with hereditary hemolytic anemias, while a predicted neutral variant demonstrated a reduced risk." (PMID 38037155, 2023). "Similarly, another predicted LOF variant in HBB, p.Glu27Lys (rs33950507), showed an association with hereditary hemolytic anemias (OR = 14.8, P = 2.51 × 10−5)." (PMID 38037155, 2023).
haemophilia A (2 papers, 2016 to 2023). "The main candidates for in vitro gene correction are monogenic diseases, such as β-thalassemia and hemophilia A. β-Thalassemia is a genetic disorder that is caused by mutations in the human hemoglobin beta (HBB) gene." (PMID 26880972, 2016).
Hepatic fibrosis (2 papers, 2013 to 2021). The presence of excessive fibrous connective tissue in the liver. "Out of 76 differentially expressed proteins, six proteins ATPD, FIBB, ATPB, HBB, CYB5A, and QCR1 were quantified across the specimens and delineated into liver fibrosis and carcinoma specific proteins." (PMID 23724895, 2013).
Insulin resistance (2 papers, 2012 to 2022). Increased resistance towards insulin, that is, diminished effectiveness of insulin in reducing blood glucose levels. "In this sense, we have found an upregulation of different genes related to hypoxia regardless of the degree of insulin resistance, such as ANGPTL4, LPL, S100A8, SLC11A2, HBB, HBA2, and HBD." (PMID 35625760, 2022).
lung disease (2 papers, 2017 to 2023). "A set of three most significantly upregulated proteins (HBB, CRP and SERPINA1) and four most significantly downregulated proteins (APOA2, AHSG, KNG1 and AMBP) were selected for validation in an independent cohort of IPF and other lung diseases using ELISA test." (PMID 28122020, 2017).
Sepsis (2 papers, 2021 to 2022). Sepsis is defined as life-threatening organ dysfunction caused by a dysregulated host response to infection. "The sub analysis of healthy versus CCI CD4+ T-lymphocytes revealed unique differential expression of five genes not seen in the analysis of all late sepsis patients (upregulated: HBB, ETS1; downregulated: SMDT1, RPL41, MTRNR2L12)." (PMID 34484194, 2021). "However, in our study, there were specific proteins only showing changes in pigs with meningitis but not in pigs with sepsis due to LPS administration, like VCL, DSC2 or HBB." (PMID 36430174, 2022).
thrombophilia (2 papers, 2021 to 2023). A condition characterized by an abnormally high level of thrombi. "Five subjects were carriers of a CFTR mutation, one female subject carried the HBB pathogenic mutation c.118C>T (p.Gln40Ter) in heterozygous status, and all subjects were found to carry at least one thrombophilia-related variant." (PMID 33401665, 2021).
acute leukemia (1 paper, 2025). A clonal (malignant) hematopoietic disorder with an acute onset, affecting the bone marrow and the peripheral blood. "The results of our study suggest that the increased expression of ACTB and the molecular interplays involving “HBA1&HBB," “HBB&HBA1," “IGKV1-5&IGHV4-31," “IGHV4-31&IGKV1-5," “HLA-DRA&CD74" and “ACTB&ACTB" might contribute to the progression of acute leukemia." (PMID 40338916, 2025). "Furthermore, the suppression of ACTB and the molecular interactions involving pairs such as “HBA1&HBB", ”HBB&HBA1", “IGKV1-5&IGHV4-31", “IGHV4-31&IGKV1-5", “HLA-DRA&CD74", and “A CTB&ACTB" might provide essential insights into unraveling the intricate mechanisms of acute leukemia." (PMID 40338916, 2025).
alopecia (1 paper, 2019). Hair loss usually from the scalp. "The differential expression of WIF1, PTPRE, HBB, and LMCD1 is associated with hair loss, morphogenesis, and alopecia." (PMID 30993080, 2019).
aphthous stomatitis (1 paper, 2021). "Using ELISA, we verified that patients with recurrent aphthous stomatitis present a high expression of HBB." (PMID 34341431, 2021). "Additionally, using western blot and ELISA assays, we verified that carbonic anhydrase 1 (CA1) and hemoglobin subunit beta (HBB) proteins are highly expressed during the ulcerative and remission phases of recurrent aphthous stomatitis." (PMID 34341431, 2021).
Arthritis (1 paper, 2024). Inflammation of a joint. "However, in the huTNFtg model of arthritis, this could not apply as the endogenous 3′UTR of the human TNF gene is replaced by the 3′UTR of the HBB gene." (PMID 39235454, 2024).
asthma (1 paper, 2021). "In bronchial epithelial cells collected by bronchoscopic brush biopsy, the expression of hemoglobin genes (HBA1, HBA2, HBB and HBD) was strongly correlated with Pre-bronchodilator FEV1 PP in patients with asthma enrolled in SARP I&II but not in controls." (PMID 34326365, 2021).
bacteremia (1 paper, 2016). "The only genome-wide significant hit for bacteremia overall was in a previously reported gene, HBB, including the well-known rs334 polymorphism associated with the production of sickle hemoglobin." (PMID 27236921, 2016).
cardiac hypertrophy (1 paper, 2021). "Network analysis mapping protein–protein interactions and synergistic actions of AR using multi-component networks reveal drug targets such as ACADM, COX4I1, COX6B1, HBB, MYH14, and SLC25A4, as potential pharmacological co-targets for cardiac hypertrophy." (PMID 33589646, 2021).
cervical cancer (1 paper, 2013). A primary or metastatic malignant neoplasm involving the cervix. "Firstly, RT-PCR experiment was performed to determine the expression levels of HBA1 and HBB genes in 20 cervical cancer samples." (PMID 23349856, 2013). "Consistent with the microarray dataset, qRT-PCR analysis showed that the expression of HBA1 and HBB was significantly higher in cervical cancer tissues than in normal cervix tissues." (PMID 23349856, 2013). "RT-PCR analysis using human blood cell RNA as a positive control showed the presence of the mRNA for the HBA1 and HBB chains of human Hgb in cultured cervical cancer cells." (PMID 23349856, 2013). "As Hgb is likely to act as heterotetramer of two different subunits, we took advantage of co-immunoprecipitation experiments to interrogate whether HBA1 and HBB expression in cervical cancer are able to form heterodimers." (PMID 23349856, 2013). "Taking advantage of commercial andibodies produced against human HBA1 and HBB, immunofluorescence analysis was performed to examine the localization of the Hgb protein in SiHa cells, which showed a similar cytoplasmic staining pattern of the HBA1 and HBB forms as that of cervical cancer tissues." (PMID 23349856, 2013). "In summary, these results suggested that both HBA1 and HBA1/HBB overexpression may have an antioxidant effect via scavenging of ROS, thus protecting cervical cancer cells against oxidative stress-induced damage." (PMID 23349856, 2013). "qRT-PCR analysis showed that Hgb-α- (HBA1) and Hgb-β-globin (HBB) gene expression was significantly higher in cervical carcinoma than in normal cervical tissues, whereas the expression of hematopoietic transcription factors and erythrocyte specific marker genes was not increased." (PMID 23349856, 2013). "Compared to normal cervix epithelium, cervical cancer samples showed a significant elevation in the expression of HBA1 and HBB genes." (PMID 23349856, 2013). "In order to validate the potential role of Hgb in human cervical carcinoma, the expression levels of HBA1 and HBB were investigated in 20 cervical cancer specimens and 10 normal cervix tissue samples by qRT-PCR analysis." (PMID 23349856, 2013).
chronic kidney disease (1 paper, 2022). Impairment of the renal function secondary to chronic kidney damage persisting for three or more months. "This study validated two loci previously reported at glycine amidinotransferase (GATM) and hemoglobin beta (HBB) loci that are associated with chronic kidney disease." (PMID 36388767, 2022).